EIF2AK4 (eukaryotic translation initiation factor 2 alpha kinase 4)
Description:
Metabolic-stress sensing protein kinase that phosphorylates the alpha subunit of eukaryotic translation initiation factor 2 (EIF2S1/eIF-2-alpha) in response to low amino acid availability. Plays a role as an activator of the integrated stress response (ISR) required for adaptation to amino acid starvation (By similarity). EIF2S1/eIF-2-alpha phosphorylation in response to stress converts EIF2S1/eIF-2-alpha into a global protein synthesis inhibitor, leading to a global attenuation of cap-dependent translation, and thus to a reduced overall utilization of amino acids, while concomitantly initiating the preferential translation of ISR-specific mRNAs, such as the transcriptional activator ATF4, and hence allowing ATF4-mediated reprogramming of amino acid biosynthetic gene expression to alleviate nutrient depletion. Binds uncharged tRNAs (By similarity). Required for the translational induction of protein kinase PRKCH following amino acid starvation (By similarity). Involved in cell cycle arrest by promoting cyclin D1 mRNA translation repression after the unfolded protein response pathway (UPR) activation or cell cycle inhibitor CDKN1A/p21 mRNA translation activation in response to amino acid deprivation. Plays a role in the consolidation of synaptic plasticity, learning as well as formation of long-term memory (By similarity). Plays a role in neurite outgrowth inhibition (By similarity). Plays a proapoptotic role in response to glucose deprivation (By similarity). Promotes global cellular protein synthesis repression in response to UV irradiation independently of the stress-activated protein kinase/c-Jun N-terminal kinase (SAPK/JNK) and p38 MAPK signaling pathways (By similarity). Plays a role in the antiviral response against alphavirus infection; impairs early viral mRNA translation of the incoming genomic virus RNA, thus preventing alphavirus replication (By similarity). (Microbial infection) Plays a role in modulating the adaptive immune response to yellow fever virus infection; promotes dendritic cells to initiate autophagy and antigene presentation to both CD4(+) and CD8(+) T-cells under amino acid starvation.
Synonyms: GCN2; KIAA1338; PVOD2
Tractability: Small molecule: a structure with a bound ligand is known; a high-quality ligand is known; it belongs to a druggable protein family. PROTAC: it is named in the literature on targeted protein degradation; ubiquitination databases record sites on it; its protein half-life has been measured; a small molecule that binds it is known.
Target class: Other protein kinase group; Other protein kinase GCN2 subfamily; Kinase; Protein Kinase; Enzyme; Other protein kinase PEK family
Gene: Protein-coding gene on chromosome 15 (39,934,115 to 40,035,736, forward strand). Ensembl gene ENSG00000128829.
Subcellular location: Cytoplasm
Subcellular location (Human Protein Atlas): Cytosol
Pathways (Reactome):
Cellular responses to stimuli: Response of EIF2AK4 (GCN2) to amino acid deficiency
Gene Ontology:
Molecular function: eukaryotic translation initiation factor 2alpha kinase activity; protein kinase activity; protein serine kinase activity; protein serine/threonine kinase activity; tRNA binding; ATP binding
Biological process: cellular response to amino acid starvation; cellular response to cold; GCN2-mediated signaling; regulation of translational initiation by eIF2 alpha phosphorylation; response to amino acid starvation; cellular response to UV; host-mediated suppression of viral genome replication; learning; long-term memory; negative regulation of neuron differentiation; negative regulation of translational initiation; negative regulation of translational initiation in response to stress; neuron projection extension; positive regulation of adaptive immune response; positive regulation of defense response to virus by host; positive regulation of long-term synaptic potentiation; positive regulation of translational initiation in response to starvation; protein autophosphorylation; protein phosphorylation; regulation of feeding behavior; regulation of translational initiation; T cell activation involved in immune response; viral translation; DNA damage checkpoint signaling; regulation of protein metabolic process
Cellular component: cytoplasm; cytosol; cytosolic ribosome; nucleus
Genetic constraint (gnomAD): Loss-of-function variants: 110 observed, 171.8 expected, observed/expected ratio (o/e) 0.64, 90% interval 0.55 to 0.75. The upper end of that interval is the gene's LOEUF score, 0.75, which puts it in group 3 of 6, group 1 being the genes least tolerant of losing a copy. Missense variants: 1,460 observed, 1,879.5 expected, observed/expected ratio (o/e) 0.78, 90% interval 0.74 to 0.81. Synonymous variants: 644 observed, 698.01 expected, observed/expected ratio (o/e) 0.92, 90% interval 0.86 to 0.99.
Gene-disease validity (ClinGen):
ClinGen rates the evidence that EIF2AK4 causes each of these diseases.
pulmonary veno-occlusive disease and/or pulmonary capillary haemangiomatosis (autosomal recessive): Definitive. A rare subgroup of pulmonary arterial hypertension (PAH) characterized by obliterative fibrosis of the small pulmonary veins and venules and/or capillary infiltration of the pulmonary interstitium leading to increased pulmonary vascular resistance and right ventricular dysfunction.
Homologues: Orthologues: chimpanzee EIF2AK4 (99% identical), macaque EIF2AK4 (99% identical), rabbit EIF2AK4 (95% identical), pig EIF2AK4 (94% identical), guinea pig EIF2AK4 (93% identical), rat Eif2ak4 (91% identical), mouse Eif2ak4 (90% identical), tropical clawed frog eif2ak4 (68% identical), zebrafish EIF2AK4 (48% identical), Drosophila melanogaster Gcn2 (31% identical). Paralogues in human: EIF2AK3 (13% identical), EIF2AK2 (10% identical), EIF2AK1 (10% identical), WEE1 (7% identical), WEE2 (7% identical), PKMYT1 (7% identical), STK35 (5% identical), PDIK1L (4% identical).
Diseases named in the same sentence as EIF2AK4 in open-access papers:
EIF2AK4 is named in the same sentence as 139 diseases in open-access papers, as found by Europe PMC text mining. Sharing a sentence is not in itself a finding about the gene and the disease. The quoted sentences say what the papers report.
viral infection (85 papers, 2009 to 2026). "EIF2AK4/GCN2 is sensitive to amino acid starvation, UV irradiation, proteasome inhibition and viral infection." (PMID 30533021, 2018). "Among these, the EIF2AK4 gene has been identified to phosphorylate eIF2α on serine 51 and rapidly inhibit translation initiation in response to a wide variety of stress-induced signals including heat shock, oxidative stress, and virus infection." (PMID 31248194, 2019). "The ISR is activated in response to many different types of cellular stress (including amino acid starvation and viral infection) and is mediated by four different cellular kinases, EIF2AK1 (HRI), EIF2AK2 (PKR), EIF2AK3 (PERK) and EIF2AK4 (GCN2)." (PMID 39951426, 2025). "Silencing of PERK eliminated the increase in eIF2α-P, contrary to silencing GCN2 (eIF2AK4) and PKR (eIF2AK2), the kinases that primarily respond to ribosome collisions, amino-acid starvation, and viral infection." (PMID 37609272, 2023). "Furthermore, a body of studies reported that the EIF2AK4 gene was also activated by other sources of stress that are not directly related to nutrient deprivation in response to specific stress signals such as UV irradiation, virus infection, and thermal stress." (PMID 31248194, 2019). "An excellent example of this concept is the identification of a gene signature including C1QB and EIF2AK4, which correlated with and predicted CD8+ T cell responses to the yellow fever vaccine with a high degree of accuracy." (PMID 22241978, 2011). "For example, the complement protein C1qB, the eukaryotic translation initiation factor 2 alpha kinase 4 EIF2AK4, and B cell growth factor TNFRS17 have been identified as key molecules for the induction of protective adaptive immune response by human yellow fever vaccine." (PMID 37298266, 2023).
pulmonary veno-occlusive disease (25 papers, 2014 to 2025). "Heritable pulmonary veno-occlusive disease is related to biallelic mutations in EIF2AK4 which encodes GCN2." (PMID 36901714, 2023). "The eukaryotic translation initiation factor 2 α kinase 4 gene (EIF2AK4) codes for a member of a family of kinases that regulates protein synthesis, and mutations in this gene seem to cause pulmonary veno-occlusive disease." (PMID 36140716, 2022). "EIF2AK4 gene has been identified as disease-causing in patients with pulmonary veno-occlusive disease (PVOD) and pulmonary capillary hemangiomatosis (PCH) in patients." (PMID 33805595, 2021). "Biallelic variants in eukaryotic initiation translation factor (EIF2AK4) cause pulmonary veno-occlusive disease (PVOD) and pulmonary capillary hemangiomatosis (PCH)." (PMID 33971972, 2021). "In the first report, numerous mutations in the EIF2AK4 gene were linked to pulmonary veno-occlusive disease (PVOD), which is characterized by obstruction and blockage of pulmonary veins by fibrous, collagen rich tissue." (PMID 24917879, 2014). "PKR, for example, could have important links to regulatory mechanisms involved in pulmonary vascular remodeling as mutations in one of the other integrated stress response kinases, EIF2AK4, are associated with pulmonary veno-occlusive disease." (PMID 32354189, 2020). "One of the hypermethylated DMRs that is associated with mRNA downregulation involves eukaryotic translation initiation factor 2α kinase 4 (EIF2AK4), a known PAH gene, which underlies pulmonary veno‐occlusive disease." (PMID 40274312, 2025). "Biallelic mutations of EIF2AK4, which encodes the kinase GCN2, are causal in two ultra-rare subtypes of PAH, pulmonary veno-occlusive disease and pulmonary capillary haemangiomatosis." (PMID 38776952, 2024). "Current studies have shown that EIF2AK4 is a key gene in the progression of pulmonary veno-occlusive disease." (PMID 34977159, 2021). "Recently, two rare subtypes of PAH, pulmonary veno-occlusive disease (PVOD) and capillary haemangiomatosis, were shown to be caused by mutations of EIF2AK4, which encodes the kinase GCN2." (PMID 29609607, 2018). "Three African American and 16 Caucasian patients, including 1 with pulmonary veno-occlusive disease and 1 with pulmonary capillary hemangiomatosis, had mutations in the bone morphogenetic protein receptor type 2 (BMPR2), Caveolin 1 (CAV1) or EIF2AK4 gene." (PMID 27224443, 2016). "A distinct form of PAH, pulmonary veno-occlusive disease (PVOD) or pulmonary capillary hemangiomatosis (PCH), was shown recently to be caused by homozygous mutations in eukaryotic translation initiation factor 2 alpha kinase 4 (EIF2AK4), a kinase in the integrated stress response." (PMID 35811711, 2022). "Two more separate identities in PAH WHO Group 1 are pulmonary veno-occlusive disease (PVOD), which can be heritable (eukaryotic translation initiation factor 2α kinase EIF2AK4 mutation), associated with autoimmune diseases or idiopathic, and persistent pulmonary hypertension of the newborn (PPHN)." (PMID 32092864, 2020). "Single‐cell RNAseq analysis was performed on the lungs of a model of hereditary pulmonary veno‐occlusive disease (hPVOD; a rare form of PAH), created in rats using an EIF2AK4 (alias: GCN2) knockdown." (PMID 40274312, 2025). "Recessive mutations of EIF2AK4 gene (encoding general control nonderepressible 2 kinase, GCN2) are linked to heritable pulmonary veno-occlusive disease (PVOD) in patients but rarely in patients with PAH." (PMID 39316438, 2024). "For example, multiple genes in the AT1 cell program were closely related to pulmonary veno-occlusive disease (PVOD) (Bmpr2 and Eif2ak4), lung cancer (Itga9 and Braf), pulmonary fibrosis (Cadm1 and Itgb6), pulmonary hypertension (Bmpr2 and Cav1), and pulmonary emphysema (Itgb6)." (PMID 34873160, 2021).
pulmonary veno-occlusive disease (continued). "This identified a novel homozygous pathogenic EIF2AK4 variant c.641delA p.(Lys214Argfs*21) in one family with two affected sisters clinically characterized as HPAH, albeit pulmonary veno-occlusive disease could not be excluded retrospectively." (PMID 33036198, 2020).
pulmonary hypertension (22 papers, 2014 to 2025). Increased pressure within the pulmonary circulation due to lung or heart disorder. "It is suggested that EIF2AK4 variants are specific to PVOD/PCH and that finding biallelic EIF2AK4 variants in a patient with pulmonary hypertension would be diagnostic of PVOD/PCH." (PMID 32471403, 2020). "The first report of a mutation in EIF2AK4 reponsible for hereditary pulmonary arterial hypertension came as a combined heterozygous mutation in conjunction with a BMPR2 mutation." (PMID 31711431, 2019). "In this study we assessed if EIF2AK4 mutations occur also in a family with autosomal dominantly inherited pulmonary arterial hypertension (HPAH) and incomplete penetrance of bone morphogenic protein receptor 2 (BMPR2) mutations." (PMID 27809840, 2016). "In human, mutations in EIF2AK4, encoding GCN2, cause a loss of function associated with pulmonary veno‐occlusive disease (PVOD), a rare form of pulmonary arterial hypertension." (PMID 35466425, 2022). "Unexpectedly, loss of GCN2 kinase activity in Eif2ak4–/– mice with genetic disruption of the kinase domain induced neither PVOD nor pulmonary hypertension (PH) but inhibited hypoxia-induced PH." (PMID 39316438, 2024). "EIF2AK4 significantly regulated the pulmonary hypertension-related disease class." (PMID 35740428, 2022). "Finally, one patient was found to harbor a pathogenetic mutation in EIF2AK4, a gene already associated to PVOD14, an uncommon form of pulmonary hypertension with a preferential involvement of the pulmonary post-capillary system." (PMID 30679663, 2019). "EIF2AK4 expression leads to pulmonary vascular remodeling, pulmonary telangiectasia, a proliferation of vascular cells, and an increase in typical metabolites in oxidative stress, which are very important for the physiology and pathology of pulmonary hypertension." (PMID 36611783, 2023). "Finally, PVOD (and PCH) is uniquely associated with biallelic EIF2AK4 mutations, a genetic hallmark not observed in ILD-associated pulmonary hypertension." (PMID 41283568, 2025).
Pulmonary capillary hemangiomatosis (10 papers, 2016 to 2025). Pulmonary capillary hemangiomatosis (PCH) is a rare form of pulmonary arterial hypertension (PAH, see this term) characterized by a capillary infiltration of the pulmonary interstitium, bronchioles and pleura leading to elevated pulmonary arterial resistance and right heart failure. "EIF2AK2 is homologous to the known PAH pathogenic gene EIF2AK4, a diagnostic marker of pulmonary venous occlusive disease and pulmonary capillary hemangiomatosis." (PMID 34336829, 2021). "Patient #17 died while on trametinib therapy, out of pulmonary capillary hemangiomatosis, a form of vascular lung disease typically associated with bi-allelic EIF2AK4 variants in its heritable form or secondary to various parenchymal lung disorders, but not typical associated NS." (PMID 40041314, 2025). "Patients with sporadic or familial pulmonary veno-occlusive disease/pulmonary capillary hemangiomatosis (PVOD/PCH) may be subjected to screening for eukaryotic translation initiation factor 2-alpha kinase 4 (EIF2AK4) mutations." (PMID 38673717, 2024).
Hepatic steatosis (9 papers, 2013 to 2024). Steatosis is a term used to denote lipid accumulation within hepatocytes. "Of note, mice deficient in EIF2AK4 exhibit resistance to obesity and hepatic steatosis induced by high fat diet and streptozotocin-induced diabetes is associated with elevated abundance and activity of RPS6KA3 in skeletal muscle." (PMID 39446839, 2024).
breast carcinoma (8 papers, 2010 to 2021). "Consistent with our results, a recent study showed that the two eIF-2α kinases, eIF2AK3 and eIF2AK4, contributed to paclitaxel response in breast cancer." (PMID 32615282, 2020). "Here, we showed that paclitaxel, the major chemotherapy drug for breast cancer, induced ISR and phosphorylated ser51 residue of EIF2S1 by EIF2AK3 and EIF2AK4." (PMID 31211507, 2019). "Therefore, the ISR in breast cancer cells after paclitaxel treatment may be induced by a co‐ordinated effect conferred by EIF2AK3 and EIF2AK4." (PMID 31211507, 2019).
diabetes (7 papers, 2021 to 2024). "PheWAS analysis of the eight candidate susceptibility genes revealed that four candidate genes (CYP19A1, EIF2AK4, EVI2A and SNX11) associated with 56 traits related to seven phenotypic categories: anthropometric, bone health, cardiovascular, diabetes, hematopoiesis, liver function, and sex hormones." (PMID 34675350, 2021). "The ISR pathway that activates the GCN2/EIF2AK4 and CHOP/DDIT3 along with other genes may influence the development of age-associated diseases, including cancer, neurodegeneration, diabetes, other, and through them, lifespan and survival traits." (PMID 34825130, 2021).
lung carcinoma (6 papers, 2021 to 2025). "Several genes of AT2 core program were strongly associated with lung disease such as lung cancer (Mvp and Braf), pulmonary fibrosis (Parn), and PVOD (Eif2ak4)." (PMID 34873160, 2021).
glioma (4 papers, 2018 to 2024). A benign or malignant brain and spinal cord tumor that arises from glial cells (astrocytes, oligodendrocytes, ependymal cells). "EIF2AK4 was also identified in a ferroptosis-associated gene signature in glioma, while concurrent dysregulation of ferroptosis and the SLIT/ROBO signaling pathway has been associated with low-grade endometrial cancer." (PMID 36497269, 2022).
hepatocellular carcinoma (4 papers, 2017 to 2024). A malignant tumor that arises from hepatocytes. "MRPL54, EZH2, PPARGC1A, and EIF2AK4 were identified as hub genes in bioinformatics analysis of hepatocellular carcinoma (HCC)." (PMID 35719986, 2022).
Crohn disease (3 papers, 2018). A gastrointestinal disorder characterized by chronic inflammation involving all layers of the intestinal wall, noncaseating granulomas affecting the intestinal wall and regional lymph nodes, and transmural fibrosis. "In fact the most DE miRNA in this study (bta-miR-374) also potentially targeted a transcription factor (EIF2AK4) known to be important for human Crohn’s disease." (PMID 30208606, 2018).
endometrial cancer (3 papers, 2021 to 2025). Primary or metastatic malignant neoplasm involving the endometrium (mucous membrane that lines the endometrial cavity). "Three of the TWAS candidate susceptibility genes (EIF2AK4, SKAP1, and SNX11) have been recently identified as potential regulatory targets of endometrial cancer GWAS risk variation through enhancer-promoter chromatin looping studies." (PMID 34675350, 2021). "Subsequent causal inference test by MR-JTI revealed two candidate genes for endometrioid endometrial cancer susceptibility (SNX11 and EIF2AK4), both of which had been identified in the main MR-JTI analysis using all endometrial cancer cases." (PMID 34675350, 2021). "To prioritise the genes identified by JTI, we performed a Mendelian randomization (MR) causal inference analysis in the respective tissues using MR-JTI, providing five candidate endometrial cancer susceptibility genes: CYP19A1, SNX11, AC021755.3, EEFSEC, and EIF2AK4." (PMID 34675350, 2021). "AC021755.3, a long non-coding RNA with unknown function, is located ~43 kb downstream of EIF2AK4 and has not been previously related to endometrial cancer." (PMID 34675350, 2021).
osteosarcoma (3 papers, 2015 to 2026). A usually aggressive malignant bone-forming mesenchymal neoplasm, predominantly affecting adolescents and young adults. "Across all Ewing and osteosarcoma cell lines eleven genes were found to be either significantly (P < 0.05, Bonferroni correction) repressed (KIF20A, IDH1, SCD, GPSM2, EIF2AK4, HIBCH) or induced (STK19, DNAJC24, MTG2, FAM175B, CYB5D1) following non DNA-damaging XI-006 treatment (0.5 μM)." (PMID 26095524, 2015).